ALB (albumin)
Diseases named in the same sentence as ALB in open-access papers (continued):
Sharing a sentence is not in itself a finding about the gene and the disease.
Ascites (continued). "When utilizing large-volume paracentesis for the management of ascites, administration of intravenous albumin 20% to 25% (at least 6 - 8 grams per liter of ascites removed) is necessary to avoid large volume shifts from the intravascular space." (PMID 32284909, 2014). "The body mass index predicted poor HRQOL independently of the presence of ascites and albumin level." (PMID 24490061, 2013). "For severe or tense ascites, large volume paracentesis with albumin infusion is required along with continued use of diuretics." (PMID 21994871, 2011). "It is calculated by adding the individual scores assigned to ranges of serum albumin level, serumbilirubin level, prothrombin time, the presence and degree of ascites and hepatic encephalopathy." (PMID 21994876, 2011). "In cirrhotic patients with refractory ascites, hyperoncotic albumin increased the treatment response rate, shortened hospital stay and reduced costs of care." (PMID 18318896, 2008). "Of these, the factors carrying the most ominous implications are those denoting the presence of liver failure, that is, a low serum albumin, elevated bilirubin and the presence of ascites." (PMID 12865918, 2003). "Clinical, pathological, and laboratory data - including peritoneal implantation stage, ascites grade, Eastern Cooperative Oncology Group performance status, serum albumin, hemoglobin, neutrophil-to-lymphocyte ratio, and treatment modalities - were collected and analyzed." (PMID 41861180, 2026). "Ascites is an uncommon manifestation of WD, possibly resulting from malabsorption that leads to protein-losing enteropathy and hypoproteinemia, and a serum-ascites albumin gradient (SAAG) lower than 1.1." (PMID 40046384, 2025). "Comparing to the previous study, we added three various (course of diseases, ALT and ALB) in model 1 and replace clinical classification (splenomegaly or ascites) with frequency of ascites based on univariate and multivariate cox proportional hazards regression analysis." (PMID 40424464, 2025). "Interestingly, in this case, ascites volume and body weight varied in direct proportion, whereas increases in serum albumin and hemoglobin inversely correlated with ascites accumulation." (PMID 40062165, 2025). "They had a more advanced disease as documented by more frequent presence of encephalopathy and ascites, as well as higher levels of bilirubin, lower serum albumin and PT-INR prolongation, resulting in higher CP and Model for End-stage Liver Disease (MELD) scores." (PMID 40392481, 2025). "Apart from the inconsistency in therapeutic effects of long-term albumin infusion, there was also debate on whether there is a magic figure for serum albumin that one should aim for while treating patients with ascites." (PMID 40143117, 2025). "First, it contains overlapping factors; that is, ascites are accompanied by albumin (Alb) levels." (PMID 41008815, 2025). "Albumin and INR were associated with ascites in MASH patients." (PMID 40591542, 2025). "At univariable Cox regression analysis, NLR ≥ 2.42, age, Child–Pugh classes, MELD score, the presence of ascites, encephalopathy, HCC, PVT, lower baseline values of serum albumin, higher values of bilirubin and INR were all associated with mortality during the follow-up." (PMID 40392481, 2025). "Long-term albumin infusion was studied to prevent the progression of ascites." (PMID 40143117, 2025). "Ascites was classified into high and low serum albumin-ascites gradient types." (PMID 39119441, 2024). "The assessment of albumin production capacity may serve as an additional indicator of liver function in the context of ascites." (PMID 38396896, 2024). "Thus, albumin infusion helps prevent paracentesis-induced circulatory dysfunction, a complication that occurs when treating ascites." (PMID 38551716, 2024).
Ascites (continued). "While an AWD was almost all cases (21/22) associated with an SSI, only one patient had a ‘classical’ burst abdomen situation (on postoperative day 2) with ascitic leakage and evisceration (♂/68 yrs, hepatocellular carcinoma, liver resection, hepato-renal syndrome, ascites, low albumin etc.)." (PMID 38285168, 2024). "Albumin was compatible with the NRS-2002 with regard to ascites, platinum-sensitivity and age." (PMID 38339372, 2024). "Albumin can be used in combination with diuretics in the treatment of ascites." (PMID 38551716, 2024). "Patients with MHE also had a lower ALB level and a higher proportion of ascites." (PMID 38369632, 2024). "Other factors may have a more significant impact on the occurrence of HRS during hospitalization, as shown in this study, such as serum albumin, bilirubin levels, the presence of ascites, and the use of vasopressors." (PMID 38752039, 2024). "The Child–Pugh classification is based on two subjective clinical features (encephalopathy and ascites) and three biochemical measures (serum bilirubin, serum albumin, and INR) whereas NCI-ODWG is based on only two biochemical markers (total bilirubin and AST)." (PMID 38675225, 2024). "In addition, the CTP classification system incorporates five different factors, including serum levels of total bilirubin, albumin, and prothrombin time, and two clinical symptom indicators, ascites and hepatic encephalopathy." (PMID 38721021, 2024). "It included ascites, hepatic encephalopathy (HE), nutritional status, total bilirubin, and albumin." (PMID 39125482, 2024). "Nonetheless, it cannot be ruled out that other factors such as liver function classification, the presence of ascites, and low albumin levels could also contribute to these results." (PMID 39151488, 2024). "Serum creatinine, albumin, bilirubin, and the presence of ascites are useful markers to predict the development of HRS in cirrhotic patients and could potentially help guide drug therapy." (PMID 38752039, 2024). "Factors that appear to be reliable in evaluating potential risks include blood albumin levels, the presence of ascites, the complexity of the surgery (e.g., stoma placement, residual bowel length, number of bowel resections), general performance status, and frailty." (PMID 39064252, 2024). "Many studies examined this aspect and found correlations between survival and prognostic factors such as low albumin or elevated blood urea nitrogen or alkaline phosphatase or clinical factors like age, radiotherapy, ascites, carcinomatosis, multiple obstructions, or a palpable mass." (PMID 39064252, 2024). "Therefore, subsequent higher production of albumin BCAAs supplementation can increase an osmotic pressure, which results in extracellular fluid reduction and can lead to ascites progression." (PMID 37189711, 2023). "However, the Child–Pugh scoring system includes some subjective indices (hepatic encephalopathy and ascites) and interrelated indices (serum albumin level and ascites), which virtually increase the instability of the prediction in different studies." (PMID 36823660, 2023). "The CP scoring system could be easily used as it comprised five variables (i.e., serum bilirubin, albumin, prothrombin time, ascites, and encephalopathy)." (PMID 36984593, 2023). "In the drug withdrawal group, liver enzymes were significantly increased in six patients, bilirubin was significantly increased in five patients, coagulation time was prolonged in five patients, albumin was decreased in three patients, and ascites was observed in one patient after withdrawal." (PMID 37491953, 2023). "Patients with high SAT radiodensity were significantly more likely to be male, have muscle atrophy and ascites, display lower body mass index, have reduced albumin levels, exhibit lower PMI in males, and have a worse Child–Pugh grade compared to those without it." (PMID 37867493, 2023).
Ascites (continued). "Backward elimination in the final logistic regression and validated weighted transformation procedure resulted in: HELP scale = (functional status × 11) + (ascites × 3) + (SBP × 3) + (HE × 4) + (dialysis × 5) + (TIPS × −3) + (albumin × −3) + (MELD‐Na ≥ 21 × 20)." (PMID 37125249, 2023). "Use of albumin replacement and increased oral protein intake helps ascites mobilization." (PMID 37396918, 2023). "However, it is weak because of the subjectivity involved in assessing ascites and encephalopathy, and by the correlation between ascites and serum albumin levels." (PMID 36484470, 2023). "Ascites due to reduced oncotic pressure only occur when albumin concentrations are below 1.5 mg/dL." (PMID 37627468, 2023). "Large-volume paracentesis with albumin could be necessary for uncontrolled ascites or renal insufficiency." (PMID 36676081, 2023). "Therefore, in patients with clinical ascites, large-volume abdominal paracentesis should be performed preoperatively, with intravenous administration of albumin in a dose of 8 g for each liter of ascitic fluid removed." (PMID 36676081, 2023). "There were statistically significant differences in varicosis degree, infection, ascites, portal vein thrombosis or cancer thrombus, child Pugh grade, albumin and prothrombin activity between the failed Endoscopy group and the successful hemostasis group (P< 0.05)." (PMID 38357146, 2023). "Promising data derived from the ANSWER study, a randomized clinical trial in cirrhotic patients with grade 2 or 3 ascites, which tested the efficacy of chronic albumin supplementation (40 g twice weekly for 2 weeks, and then 40 g for up to 18 months) on top of the standard of care." (PMID 36769582, 2023). "This may be because the Child-Pugh scoring system involves some subjective indexes (hepatic encephalopathy and ascites) and interrelated indexes (serum albumin and ascites), which virtually increase the instability of the prediction in different studies." (PMID 36733609, 2023). "Several studies have also evaluated the impact of chronic use of albumin in patients with ascites." (PMID 36769582, 2023). "In addition, the SMV group tended to have higher Child–Pugh score (mainly derives from lower albumin level and more severe ascites), higher model for end-stage liver disease score (mainly derives from higher INR level) and lower pre- and post-TIPS PPG." (PMID 35906529, 2022). "Moreover, they found that those patients had lower serum albumin values compared to those with high gradient ascites." (PMID 35178310, 2022). "In addition, we found that rs34486793 and rs106520 are significantly related in the ascites grade phenotype (P = 7.73 × 10-5 and 2.61 × 10-5, respectively), and rs983360 also had a significant correlation in the serum albumin phenotype (P = 7.83 × 10-5)." (PMID 35493725, 2022). "In four of the six patients, the Child-Pugh score was elevated by 1 point; the Child–Pugh score was elevated in three patients (A5→A6) due to a decrease in albumin level to <3.5 and in one patient (B8→B9) because of the presence of a small amount of new ascites on follow-up CT." (PMID 35207584, 2022). "However, a previous study suggested reversible deterioration of MELD score with midodrine, octreotide, and albumin treatment for one month in refractory ascites." (PMID 36060403, 2022). "Moreover, the impact of hepatic function (i.e., especially albumin) on the clinical outcomes is distinct for different ascites severity grades." (PMID 35845294, 2022). "However, the CTP score is calculated using five variables: ascites, encephalopathy, PT, and serum levels of bilirubin and albumin." (PMID 35139804, 2022). "The selection of cut points for the continuous variables (the bilirubin, albumin, and prothrombin time), and the subjectivity in the use of the categorical variables (hepatic encephalopathy and ascites), leads to decreased discrimination power for the prognosis prediction." (PMID 35845571, 2022).
Ascites (continued). "The production of ascites and its volume mainly depend on the portal vein pressure, though that might be influenced by the albumin level." (PMID 35845571, 2022). "Univariate survival analysis using the Cox proportional hazards model in the HH group has shown that total bilirubin, kidney dysfunction, and HRS during the hospital stay, sodium levels, serum albumin, grade III ascites, SBP, MELD-Na, and ALBI score and ALBI grade were associated with survival." (PMID 34441984, 2021). "After Y90-RE therapy, the within MC group demonstrated a lower incidence of ascites (12% vs. 26%; p = 0.03), lower levels of alkaline phosphatase (124 ± 58 U/L vs. 161 ± 114; p = 0.02), and higher levels of albumin (3.6 ± 0.5 g/dL vs. 3.3 ± 0.6 g/dL; p = 0.004) than the outside MC group." (PMID 34336728, 2021). "The preoperative albumin level is correlated with surgical outcomes related to refractory ascites." (PMID 34107967, 2021). "• Patients with uncomplicated ascites may benefit from the long-term administration of albumin given that renal dysfunction and HRS-AKI presumably are prevented by modulation of systemic inflammation." (PMID 34131658, 2021). "Having a small study population rendered the multivariate analysis unreliable, where no ascites, low serum albumin (not high), and GPS-L status were significantly associated with better OS." (PMID 33635904, 2021). "Ascites are usually managed with diuretics and restriction of sodium intake, with severe cases (tense ascites) that require repeated paracentesis coupled with albumin replacement." (PMID 34829792, 2021). "After 12 months of FIR therapy, the patient’s ascites fluid became even lighter in color and there was further improvement in the nutritional status with a significant increase in the serum albumin level from 2.7 g/dL to 4.2 g/dL and body weight from 59.1 kg to 62.9 kg." (PMID 34564486, 2021). "Although albumin is more widely used in clinical practice, albumin was primarily associated with colloid osmotic pressure and ascites rather than rigorous nutritional support." (PMID 34022800, 2021). "When only patients with SIRS were analyzed, univariate Cox regression showed that survival was related to the presence of ascites, HE, bacterial infection, sodium, albumin, INR, total bilirubin, creatinine, leukocyte count, CRP, MELD score, ACLF, and Child-Pugh C." (PMID 33987144, 2021). "Previous studies demonstrated that low albumin was a common complication in cirrhotic patients that could lead to ascites or edema, and accounted for increased mortality." (PMID 34355041, 2021). "However, this system includes subjective factors such as hepatic encephalopathy and ascites, and interrelated factors such as serum albumin and ascites." (PMID 34262065, 2021). "However, a major problem of the C–P classification system is that it involves two subjective elements (ascites and encephalopathy) and interrelated elements (serum albumin and ascites)." (PMID 32121095, 2020). "For example, ascites could be affected by diuretics, and albumin level could be changed by intravenous infusion." (PMID 33336028, 2020). "When facing a patient with new-onset ascites it might be cumbersome to differentiate cardiac ascites from cirrhotic ascites as in both conditions the serum-ascites albumin gradient is ≥1.1 g/dL as a result of hepatic sinusoidal hypertension." (PMID 33321947, 2020). "Contrarily, patients with ascites presented significantly lower serum albumin and MAC." (PMID 33003490, 2020). "Most of the patients of our study were in stage B and stage C. The BCLC staging was determined according to the patients' albumin, bilirubin, ascites, encephalopathy, imaging reports, tumor size, portal vein invasion, tumor site, Child-Pugh score, and prothrombin activity." (PMID 32339207, 2020). "Ascites is easy to occur when the ALB level below the normal level." (PMID 32503634, 2020).
Ascites (continued). "However, the C–P score/classification system includes subjective components, such as ascites and encephalopathy, and interrelated factors such as serum albumin and ascites." (PMID 33082429, 2020). "Moreover, the Δ serum albumin level of CART gradually increased with the volume of drained ascites, while that of the paracentesis group decreased." (PMID 31308465, 2019). "Furthermore, some of these factors are correlated and thus duplicative (albumin, ascites) and some are subjective (ascites, encephalopathy)." (PMID 31238514, 2019). "However, the CTP classification not only includes objective biosynthetic parameters such as circulating albumin, bilirubin and coagulation characteristics, but also more subjective parameters such as the presence and severity of ascites and encephalopathy." (PMID 30917853, 2019). "However, the major limitation of this system is that it includes several subjective components (hepatic encephalopathy and ascites) and interrelated components (serum albumin and ascites)." (PMID 31766742, 2019). "However, the major drawback of the Child-Pugh classification is that it involves several subjective factors (ascites and hepatic encephalopathy) and interrelated factors (ascites and serum albumin)." (PMID 31159435, 2019). "In addition to short-term administration to acutely decompensated patients, the efficacy of long-term albumin administration in patients with ascites has recently been investigated in a randomized, multi-site trial." (PMID 30873165, 2019). "The Child‐Pugh‐Turcotte score (CPT), which requires measurement of five clinical and laboratory variables (prothrombin time; albumin values; presence and degree of encephalopathy; presence and degree of ascites; and bilirubin levels), should be performed before the start of any DAA treatment." (PMID 29633552, 2018). "Parameters related to hepatic injury (aspartate aminotransferase [AST]/alanine aminotransferase [ALT]), severity of disease (ascites) and synthesis function (albumin) as well as AC, rates of PVT regression/progression and AC-associated complications were documented." (PMID 29916054, 2018). "Furthermore, pre-operative refractory ascites should be managed with paracentesis and albumin/electrolytes serum level and coagulation alteration with appropriate correction." (PMID 30065783, 2018). "However, the CP classification is limited by subjectivity in assessing hepatic encephalopathy and ascites, and inter-relationships between the serum albumin level and ascites." (PMID 29988960, 2018). "It is tempting to conclude that a combination of human albumin plus stem cells may have a more potentiating action for containment of ascites and this should be checked in a large cohort with adequate power and controls." (PMID 30828553, 2018). "Moreover, factors associated with SPH, such as etiology, Child-Pugh score, ascites, AST values, ALT values, ALB, GGT, total bilirubin, PLT count, prothrombin time and INR, were significantly associated with the presence of SPH." (PMID 28820885, 2017). "Finally, factors associated with HVPG grade were etiology, Child-Pugh score, ascites, AST values, ALT values, ALB, PLT count, prothrombin time and INR." (PMID 28820885, 2017). "In addition, he received an albumin infusion on day 5 after he developed clinical ascites with a further drop in his albumin to 17 g/L." (PMID 27906062, 2016). "Additionally, increased circulating AOPPs-albumin level, along with hs-TnT levels in decompensated cirrhotic patients, especially higher values in refractory ascites group, were observed in this study." (PMID 26665009, 2015). "Albumin infusion can increase the cardiac index in HRS patients with refractory ascites." (PMID 26606982, 2015). "AOPPs-albumin positively correlated with the hs-TnT, both when the whole group of cirrhotic patients was evaluated (r = 0.28, P < 0.05) and when correlation analysis was limited to patients with ascites (r = 0.35, P < 0.01)." (PMID 26665009, 2015).